CCL5 (C-C motif chemokine ligand 5)
Diseases named in the same sentence as CCL5 in open-access papers (continued):
Sharing a sentence is not in itself a finding about the gene and the disease.
infection (continued). "Whether EHV-1 infection is activating the attraction of CD172a+ monocytic cells to the infection sites and whether CCL2 and CCL5 are driving forces during this process are largely unknown." (PMID 28241864, 2017). "Expression of Cd3d, Cd8a, Ifn, Ccl5 and Tbx21 remained highly upregulated 56 days post-infection whereas Ccr7 did not." (PMID 29040326, 2017). "The viral ligand U83A is produced early in infection and binds CCR5, which blocks binding by CCL5." (PMID 29194419, 2017). "However, infection with the miR-US5-1/miR-UL112-3p mutant virus still enhanced IL-6 and CCL5 levels above that observed with WT infection." (PMID 28270578, 2017). "Levels of IL-1β, IL-6, CCL2, CCL3 and CCL5, which are known to play an important role during HSE, were measured in brain homogenates using magnetic bead-based immunoassays prior to (day 0) and on days 6, 8 and 10 following infection." (PMID 27930721, 2016). "After infection or administration of a contact sensitizing agent, there is a sustained increase in skin CD4+ T-cell content, which is confined to the clusters, with a concomitant CCL5-dependent increase in CD4+ T-cell recruitment." (PMID 27160938, 2016). "We therefore examined gene expression for several important interferon-related genes (IFNα2, IFNα4, IFNβ, IFNαβR, IFNγ, IFNγR, Irf3, Irf7, Mx1, Oas1, IFITM1, IFITM2), along with inflammasome-related genes IL-1β and NLRP3, and chemokines CCL5, CCL7, and CCL12 at d1 post-infection." (PMID 26110868, 2015). "On the other hand, the levels of CCL17, CCL21 and CCL22 were not affected by FusOn-H2 infection, and CCL5 was actually reduced by the virus treatment." (PMID 25460506, 2015). "Yet, a strong early wave of CCL5 proved to be MC-derived and is likely important for the kick-start of an efficient CD8 T-cell infiltration and consequently reduced peak viral load and accelerated clearance of the productive infection of the lungs." (PMID 24763809, 2014). "CCL5, CCR1, CCR3 and CCR5 mRNA expression was also detected in brains of Swiss Webster mice and appeared to contribute to the inflammatory response that results in cellular degradation in the cerebellum during Plasmodium yoelii (17XL) infection." (PMID 24476686, 2014). "Consistent with the trend of NF-κB activity, the expression levels of three of the four selected chemokines regulated by NF-κB (Ccl2, Ccl3, Ccl5, but not Cxcl1), peaked on day 32 post-infection." (PMID 25116007, 2014). "Indeed, Met-CCL5 significantly protected adult mice from the infection of the street strain HN10, especially at the early stage of infection." (PMID 25182681, 2014). "Expression of IFN-β and CCL5 48 h after infection was confirmed by ELISA and was not seen in UV-DENV treated cells, showing that viral replication was necessary to induce innate immune gene up-regulation." (PMID 25474532, 2014). "We therefore analyzed absolute serum levels of CCL5 in immunocompetent C57BL/6 mice in response to intravenous infection in a time course and found peak levels on day 2 post-infection with a ca. 5-fold induction compared to pre-infection levels, which is quite substantial." (PMID 24763809, 2014). "Recruitment of effector cells of the innate or adaptive arm of the immune system by MC-derived chemokines, such as CCL5/RANTES, to sites of infection could be such a common mechanism for the contribution of MC to virus containment." (PMID 24763809, 2014). "In this context, there is a marked induction of CCL2, CCL3, CCL4, CCL5, CXCL8, and CXCL10 after infection with SIV, as well as a systemic increase of CCL2, CXCL8, and CXCL10 in humans, concurrently with viremia peak after infection with HIV." (PMID 25313360, 2014). "Furthermore, our study also showed decreased expression of the chemokines CCL3, CCL4 and CCL5 in the liver and ileum of CCR5-/- mice along with reduced induction of the transcription factors Foxp3, T-bet and GATA-3 after infection." (PMID 25119429, 2014).
infection (continued). "CCL4 was expressed at significantly higher levels in livers of WSX-1−/− mice compared to WT mice on day 7 of infection, whereas CCL4 and CCL5, both ligands for CCR5, were expressed at 5–10-fold higher levels in livers of WSX-1−/− mice compared to WT mice on day 14 of infection." (PMID 24244314, 2013). "It has been shown that CCL5 and CCL2 expression, detectable following infection with a HCMV strain Towne US28 deletion mutant, could induce monocyte chemotaxis that was inhibited by infection with the parental strain expressing US28." (PMID 23202490, 2012). "Infection with L. tropica led to increased serum levels of chemokines CCL2, CCL3 and CCL5." (PMID 22679519, 2012). "NY/238 infection markedly stimulated CXCL10 mRNA, NY/238 virus also triggered an early increase in the expression of RIG-I and IFNA1 genes and increased mRNA levels of antiviral gene ISG56 and CCL chemokine CCL5." (PMID 22396727, 2012). "Elicited macrophages from both CD200R1+/+ and CD200R1−/− mice were infected with HSV-1 (multiplicity of infection; MOI = 10), or challenged with Pam2CSK4 (100 ng/ml), or LPS (100 ng/ml), and levels of IL-6, CCL5 (Rantes), or CCL2 (MCP-1) were measured at 24, 48, and 72 h." (PMID 23082204, 2012). "In addition, higher concentrations of mRNA for IFN-γ CCL2 and CCL5, as well as protein, but lower numbers of apoptotic cells, were found in lesions from TNFR1 KO mice than in WT, at late time points of infection." (PMID 22203861, 2012). "CCL-5 was not significantly more abundant in R5 HIV-1-infected cell supernatants 14 days after infection (p = 0.06)." (PMID 21767373, 2011). "Similarly, the chemokines RANTES (CCL5) and KC (CXCL1) were increased with infection to a similar degree in wild type and CAT2−/− mice." (PMID 22194986, 2011). "Interestingly, chemokines which are responsible for infiltration of monocytes and macrophage like Ccl5/RANTES and Ccl4/MIP-1β showed increased expression at an acute phase of infection and increases the infiltration of monocyte and macrophages." (PMID 21371334, 2011). "Similarly, at 18 hours post-H9N2/1997 infection, CCL-5/RANTES mRNA expression was found to be induced by nearly 1000 folds; while CXCL-10/IP-10, IL-6, and IL-8 were found to be up-regulated by 16-116 folds." (PMID 21108843, 2010). "Indeed, during L. major infection, CCL5 expression was reported to increase selectively in C57BL/6 compared to BALB/c mice, but mainly in the late phase of infection." (PMID 20140197, 2010). "Similarly for H9N2/1997 infection, there was 5-25 folds increase in the transcription of CCL-5/RANTES, TNF-α, and CXCL-10/IP-10 mRNA at 3 hours post-infection." (PMID 21108843, 2010). "Here we demonstrate the temporal correlation between a significantly stronger and transient expression of macrophage chemoattractants (CCL5, CCL2 and opn) with a peak after 8h post infection and an ensuing significantly more pronounced macrophage infiltration 3 days after infection." (PMID 20442861, 2010). "L. major induced only a small increase in CCL4 and CCL5 mRNA at the site of infection, while infection did not induce CCL20 mRNA (data not shown)." (PMID 20140197, 2010). "Acute HIV infection also induces production of chemokines (CCL2, CCL3, CCL4, and CCL5), which may recruit uninfected monocytes/macrophages and/or CD4+ T lymphocytes to the sites of virus replication, thus promoting the spread of infection and/or the establishment of virus reservoirs." (PMID 40507836, 2025). "Additionally, infection with H9N2 AIV, whether live or inactivated, induces strong innate antiviral and inflammatory responses involving TLR3, TLR7, MDA5, TNF-α, and CCL5 stimulation." (PMID 41331407, 2025). "BR15 infection induced a modest but statistically significant increase in TNF-α expression (p < 0.05) and a significantly higher expression of IFN-β1, IL-1β, IL-6, and IL-10, as well as the chemokines CCL2 (MCP-1), CCL5 (RANTES), and CXCL8 (IL-8), compared to MR766-infected cells." (PMID 40732762, 2025).
infection (continued). "However, both pre- and post- cilomilast had only a small, non-significant reductive effect on RV16-induced CCL5 protein production at 48 h RV16 infection." (PMID 39598462, 2024). "Similarly, the chemokines CCL2 (attracting monocytes), CXCL2 (attracting neutrophils), CCL5 (attracting T cells), CXCL10 (attracting activated T cells, eosinophils), and CCL11 (eosinophils) were elevated during infection with a significant reduction in TLR7 KO mice." (PMID 39769461, 2024). "However, in addition to IL-12, GRA24 upregulates several other proinflammatory cytokines and chemokines, including IL-6, TNF, MCP-1, CCL5, CXCL1, and CXCL10 that could contribute to the lethal outcome of infection." (PMID 39440975, 2024). "Interestingly only Mayotte 2008 induced an increased secretion of IFN-β, CXCL9, CXCL10, and CCL5, and only CXCL11 was increased for both RVFV strains infection." (PMID 37306630, 2023). "Interestingly, dual species infections with P. gingivalis and S. oralis decreased the expression of IL-6, IL-12 (p40), and CCL5/RANTES compared to tissue without implants." (PMID 35203495, 2022). "Interestingly, VOC Alpha infection displayed a trend to induce slightly higher levels of ISG56, MXA, and CCL5 expression than B.1, arguing against the idea that the increase of VOC Alpha-derived sgRNA transcription is linked to stronger suppression of the innate immune response." (PMID 36383605, 2022). "In such molecular instance, a CCL5 5p12 5m-C37-engaged CCR5 molecule, either in proximity or as a CCR5 dimeric partner to the gp120-bound CCR5, could provide the C37 inhibitor, readily preventing infection." (PMID 36366513, 2022). "While the extent and magnitude of gene expression changes were not as robust as the virulent ZIKV-MR766 infection model, we nevertheless saw significant changes in the expression of 7 of 14 genes analyzed, including Adora2, Cacna1e, Ccl5, Gpr84, Nlgn1, Pmch, and Tor3a." (PMID 35462541, 2022). "In contrast, the downregulation of RANTES/CCL5, MIP-1α/CCL3, and MIP-1β/CCL4 from the early to middle phase of the infection as well as the downregulation of MIG/CXCL9, IP-10/CXCL10, and IL-13 in the middle phase of the infection were observed in aged BALB/c mice." (PMID 35264719, 2022). "However, CD8A+ cells also ubiquitously showed highest levels of CCL5 (RANTES), a chemokine previously shown to maintain CD4+ TRM cells after infection or sensitization, but that also attracts monocytes which were shown to promote the survival of MF cells in a mouse model." (PMID 33968070, 2021). "Moreover, infection with the nonhuman pathogenic NW mammarenavirus Pichinde virus (PICV) p2 strain, which causes mild disease in guinea pigs, was followed by increased CCL5 expression at late time points, in contrast to the virulent PICV p18 strain." (PMID 34372519, 2021). "Our results showed that HTNV infection led to elevated cytokine production, including CXCL-1, CCL-5, IL-6, IL-12, TNF-α, and IFN-γ in Nlrc3−/− mice, and the levels of these cytokines peaked at 6 or 9 dpi; in comparison, WT mice had weaker cytokine responses throughout the infection process." (PMID 34335602, 2021). "Furthermore even by day 3 post infection we observed reduced pulmonary production of IFN-γ and key innate inflammatory cytokines monocyte chemoattractant protein-1 (MCP-1), IL-6 and C-C motif chemokine ligand 5 (CCL5, RANTES) in MR1-/- mice." (PMID 35381137, 2021). "Thus, knocking out CCL5 did not alter the ability of ZIKV to infect hBMECs or express viral proteins in hBMECs at early times after infection." (PMID 34399621, 2021). "In addition, after ZIKVBR infection, trophoblasts from the non-affected twins were able to significantly induce the secretion of immune mediator chemokines RANTES/CCL5 and IP10, while trophoblasts from the CZS-affected twins were not." (PMID 32745093, 2020).
infection (continued). "Infection with RV1b resulted in increased rhinovirus load measured via qPCR compared to UV-inactivated RV1b (31.3 ± 29.8 copy #/ng RNA vs. 2.37 × 107 ± 1.46 × 107 copy #/ng RNA; p < 0.05), increased typical pro-inflammatory viral cytokines CXCL10 and CCL5, and type I and III interferon responses." (PMID 32328066, 2020). "To identify mechanistic bases for the different numbers of neutrophils at the site of infection, we measured the main chemokine factors for neutrophil attraction, including the CCR1 ligands CCL3, CCL4, and CCL5 and the CXCR2 ligands MIP-2/CXCL-2, KC/CXCL-1, and CXCL5." (PMID 32424099, 2020). "However, this pathogenic mucoralean species exhibits immunosuppressive effects on NK cells by reducing the production levels of IFN-γ and the pro-inflammatory chemokine RANTES (CCL5), which promotes chemotaxis and migration of T cells and monocytes to the site of infection." (PMID 32957440, 2020). "Instead, we observed chemokines as particularly affected by the presence of the parasite, since IL-8, CCL3, CCL4 and CCL5 were significantly reduced in concentration in Ss+ subjects compared to CTRL, suggesting that immune cell recruitment to the infection site might be dampened in these patients." (PMID 33059754, 2020). "Infection with LCMV further increased CCL5 in Ma-Mel-86a cells, but not in Ma-Mel-51 cells." (PMID 32973762, 2020). "The cytokines CXCL8, CCL5 (also known as Regulated on Activation, Normal T Expressed and Secreted, RANTES), tumor necrosis factor α (TNF-α), CXCL1/5 and CCL3 released, promote development of a pro-inflammatory state along with the recruitment of other immune cells to the site of infection." (PMID 33102253, 2020). "Interestingly, from all the analytes tested, the chemokines RANTES/CCL5 and IP10 showed a consistent (both at 48 h and 96 h post-infection) and significant increase in secretion by trophoblasts from non-affected twins after infection with ZIKVBR, but not by trophoblasts from CZS-affected twins." (PMID 32745093, 2020). "Notably, the abundance of seven chemokines, such as C–C motif chemokine ligand 14 (CCL14), CCL20, CCL25, CCL5, C–X–C motif chemokine ligand 10 (CXCL10), CXCL14, and atypical chemokine receptor 3 (ACKR3), was significantly higher by infection in the R line of the TSF flock." (PMID 30678719, 2019). "However, it is also noteworthy that CCL5, similarly to Maraviroc and other CCR5 ligands, competes with HIV-1 protein gp120 for binding to CCR5 co-receptor, thus having a inhibitory effect on HIV-1 entry and infection." (PMID 31708924, 2019). "In addition, chemokine CCL5 secreted by virally-activated MCs was shown to more efficiently recruit antiviral CD8+ T cells to the lungs, which contributes to a faster resolution of a productive infection of the lungs." (PMID 30563202, 2018). "Cells lacking IFI16 also secreted less CCL5 protein 24 h post infection with MVA." (PMID 28194029, 2017). "Therefore, levels of CXCR3 (receptor for CXCL9 and CXCL10), CXCR5 (receptor for CXCL13), CCR5 (receptor for CCL3 and CCL5), and CCR7 (receptor for CCL19) were analyzed on CD45hiCD11bloCD19+ B cells which infiltrated the brain at 7, 14, 30, and 60 days post infection." (PMID 27207308, 2016). "Furthermore, Pkcδ-deficient macrophages produced higher amounts of IL-1α and CCL5, but not CXCL2 than WT macrophages in response to infection." (PMID 24516390, 2014). "Furthermore, the antibody array was randomly confirmed by qRT-PCR, and the results showed that pro-inflammatory chemokines including CCL5 and CCL2 and cytokines including IL-6, IL-1β, IL-12, and IL-17 were significantly enhanced after infection with aG and CTN." (PMID 25182681, 2014). "An increase in mRNA levels for a number of host immunomodulatory genes, including chemokines, CCL3, CCL5 and CXCL2 was observed at 4 h post-infection compared to mock-infected cells and a reduction to similar levels as in mock-infected cells at 16 h post-infection." (PMID 23265239, 2013).
infection (continued). "The concentrations of IL-6 and CCL5 were dependent on the dose of infectious virus and the concentration of these cytokines induced by NH1125 was greater than that of those induced by NH1067 when the multiplicity of infection of NH1067 used was as much as 10-fold higher than that of NH1125." (PMID 22962966, 2012). "To explore the possibility that SrfJ may modulate the secretion of CCL5 in host cells, we infected RAW264.7 macrophages with wild-type S. enterica serovar Typhimurium or with a ΔsrfJ mutant and measured the concentration of the chemokine in the supernatants of cell cultures 8 h post-infection." (PMID 37176110, 2023). "In our study, BVDV-2 infected goat PBMCs showed increased transcription of CCL3, CCL4, CCL5, CCL20, CXCL10 and decrease of CCL2, suggesting that such chemokines may contribute to the recruitment and regulation of macrophages or other inflammatory cells to the infected sites after infection." (PMID 31226933, 2019). "This topological inversion blocks macrophages from further migration toward CCL5, allowing macrophages to produce pro-inflammatory cytokines to combat infection at the current location instead of migrating to the cells from which CCL5 is secreted, as these cells themselves may not be infected." (PMID 30835201, 2019). "Surprisingly, compared to uninfected HIBCPP cells, infection with C. albicans did not alter the secretion of CXCL8, CCL2, and CCL5 after 24 h, respectively, which was the fact for both the basolateral (blood) and apical (CSF) side." (PMID 40181464, 2025). "Consistent with the lack of effect on BR15 infection, AbII treatment did not significantly alter the levels of IL-1β, IL-6, IL-10, CCL2 (MCP-1), CCL5 (RANTES), or CXCL8 (IL-8) in BR15-infected cells." (PMID 40732762, 2025). "When measuring mRNA expression levels from BAL cells, chemokines CCL2, CCL5, CCL8, and CXCL10 and receptors CCR5 and CXCR5 were significantly upregulated only in JBNU-22-N01 infection at 7 dpi compared with the negative control." (PMID 40459260, 2025). "Compared to the medium, UV-inactivated RV16, filtered RV16, and the non-virus 0.1% DMSO infection medium did not significantly induce IL-6, CXCL8, or CCL5 protein release." (PMID 39598462, 2024). "We found three genes that were commonly activated with infection with SCV2 at both 12 and 24 hpi (DUSP1, HES1, KLF2) and some non-congruent genes at 12 hpi (CCL5, ZBP1, NRXN2, STAB1, SLC25A47, CXCL11) and 24 hpi (FOXA2, RHOB)." (PMID 37504520, 2023). "Additional genes that were downregulated after treatment with 1,25(OH)2D3 were CCL5 and NOS2, the gene for iNOS, both of which showed a significant decrease (P < 0.05) across all groups regardless of infection status." (PMID 35211544, 2022). "CCL3 (MIP-1α) and CCL5 (RANTES) were observed in all pre- and post-infection sera without any specific change in expression level (data not shown)." (PMID 35371043, 2022). "Unlike CCL5 5p12 5m, its C37 chimeric form blocked PM1 cells infection by dual tropic R5/X4 (92US077) and X4 tropic (IIIB) HIV-1 strains." (PMID 36366513, 2022). "S. oralis infections as single species caused a significant increase in the expression of IL-1α, IL-6, IL-12 (p40), CXCL1/KC, CCL5/RANTES, and CCL11 compared to infection without implants." (PMID 35203495, 2022). "According to this, experiments in the A549 cell line (human alveolar type II-like epithelial) with the Long strain of hRSV showed that infection with hRSV induces the secretion of IL-6, CCL3, and CCL5 at 48 h post-infection as compared to non-infected cells." (PMID 30936869, 2019). "In contrast to these findings, infection with the hRSV Long strain in NHBEs cells did not lead to the secretion of CCL2 and CCL3, but the levels of CCL5 were increased as compared to uninfected cells." (PMID 30936869, 2019).